SPHK2 (sphingosine kinase 2)
Diseases named in the same sentence as SPHK2 in open-access papers (continued):
Sharing a sentence is not in itself a finding about the gene and the disease.
Alzheimer disease (7 papers, 2018 to 2025). A progressive, neurodegenerative disease characterized by loss of function and death of nerve cells in several areas of the brain leading to loss of cognitive function such as memory and language. "We have previously reported the loss of S1P and SphK2 activity early in the pathogenesis of Alzheimer’s disease, and recently demonstrated that loss of SphK2 sensitizes to hippocampal atrophy and myelin loss in a mouse model of Alzheimer’s disease." (PMID 32521763, 2020). "Our own research observed a marked accumulation of d18:2 SLs (unpublished), following the ablation of sphingosine kinase 2 (SphK2) in a mouse model for Alzheimer’s disease (J20), which led to severe defects in myelin integrity." (PMID 38388524, 2024). "Intriguingly, greater levels of SPHK2 are found in neuronal nuclei in Alzheimer’s disease (AD) brain samples than in control samples, suggesting that SPHK2 has a role in AD." (PMID 34055895, 2021). "Interestingly, Alzheimer's disease is associated with SphK2, a key player of the UFIT pathway, that unlike SphK1, is upregulated in brain samples from patients with Alzheimer's disease, and as a result leads to S1P overproduction in neurons." (PMID 39877933, 2025). "While both SPHK2 and PPIF are overexpressed and likely contribute to neuronal death in both human patients with Huntington’s disease or Alzheimer’s disease and rodent models of these diseases, knockout or inhibition of these genes protects against neurodegeneration." (PMID 40310674, 2025).
colitis (7 papers, 2016 to 2024). Inflammation of the colon. "The severity of colitis is increased by elevated COX-2 levels in Sphk2–/– mice, and Sphk2 depletion enhances Sphk1 expression." (PMID 38482014, 2024). "By upregulating the Sphk1/S1P/S1PR1 axis and activating the NF-κB and STAT3 pathways in acute colitis, experimental data suggest that Sphk2 exerts anti-inflammatory effects." (PMID 38482014, 2024). "Other studies using different models, namely, tumour cells, acute colitis and knock out mice in which Sphk2 expression was depleted, showed an increase of Sphk1 expression, activity and S1P levels." (PMID 28753653, 2017). "Although the absence of SphK1 was protective against DSS-induced colitis, SphK2 depletion resulted in enhanced proliferation and proinflammatory cytokine production, and thus IBD progression." (PMID 26880864, 2016).
gastric cancer (7 papers, 2019 to 2026). A primary or metastatic malignant neoplasm involving the stomach. "sphingosine kinase 2-mediated phosphorylation of Krüppel-like factor 2 (KLF2) triggers the degradation of KLF2 protein in gastric cancer." (PMID 41517663, 2026). "While SKI-II is considered a selective inhibitor of SK1, it also inhibits sphingosine kinase 2 and has been shown to have off-target effects on ceramide dihydroceramide desaturase 1 (Des1), leading to reduced S1P accumulation in gastric cancer cells." (PMID 30728898, 2019). "Moreover, METTL3 regulates the m6A modification of SPHK2 to promote the progression of gastric cancer." (PMID 35012593, 2022). "Several studies have reported that progression of GC is promoted by m6A writers, for example, METTL3-mediated m6A modification of some mRNA (HDGF, SPHK2, and MYC), which ultimately promotes gastric cancer progression, thus, exhibiting a prognostic significance." (PMID 35778697, 2022). "In gastric cancer, YTHDF1 recognized m6A modified SPHK2 mRNA that was catalyzed by METTL3." (PMID 36291811, 2022).
Insulin resistance (7 papers, 2018 to 2025). Increased resistance towards insulin, that is, diminished effectiveness of insulin in reducing blood glucose levels. "Remarkably, the liver-specific deficiency of Sphk2 exhibits pronounced insulin resistance and glucose intolerance, demonstrating a key role of hepatic SphK2 in the regulation of insulin sensitivity and glucose homeostasis." (PMID 34530846, 2021). "More recently, we have reported that hepatocyte-specific deficiency of SphK2 in mice increased hepatic glucose production, impaired glucose homeostasis and caused insulin resistance." (PMID 34530846, 2021). "To investigate the association of SphK2 and insulin resistance in the liver, we generated Sphk2-LKO mice." (PMID 32917816, 2020). "We then sought to identify which sphingolipid species was primarily responsible for insulin resistance under SphK2 deficiency." (PMID 32917816, 2020). "Furthermore, we identified sphingosine as a chief inhibitor of hepatic insulin signaling, which primarily accounts for the SphK2 deficiency-induced insulin resistance." (PMID 32917816, 2020). "SPHK2 has been shown to be involved in the pathology of T2DM by promoting insulin resistance and pancreatic β-cell lipotoxicity and dysfunction." (PMID 41301404, 2025). "Hepatic glucose intolerance and insulin resistance have been observed in hepatocyte-specific SphK2-knockout (SphK2−/−) mice." (PMID 38256005, 2024). "Specifically, the ablation of Sphk2 in hepatocytes led to insulin resistance both in vivo and in vitro." (PMID 32917816, 2020). "Hepatocyte-specific Sphk2 knockout mice exhibit pronounced insulin resistance and glucose intolerance." (PMID 32917816, 2020). "In muscle insulin resistance, the role of SphK1 is still under debate, while little is known about SphK2." (PMID 33633691, 2020). "Overexpression of SphK2 in the liver reinforces mitochondrial fatty acid β-oxidation and effectively ameliorates hepatic steatosis, glucose intolerance and insulin resistance in C57BL/6 mice on an HFD." (PMID 33633691, 2020). "SphK2 can be metabolically protective, as Sphk2−/− predisposes to nonalcoholic and alcoholic fatty liver diseases, whereas adenoviral overexpression of SphK2 primarily in the liver improves insulin resistance (18, –20)." (PMID 32917816, 2020). "In hepatic insulin resistance, SphK2 has been illustrated as a metabolically protective factor, whereas the effects of SphK1 are controversial." (PMID 33633691, 2020). "Hepatic overexpression of SphK2 in the KK/Ay mouse model leads to elevated S1P levels and ameliorates glucose intolerance and insulin resistance in response to a HFD." (PMID 29510489, 2018). "Additionally, adenoviral overexpression of SphK2 in the liver improves glucose intolerance and insulin resistance in diet-induced obese mice." (PMID 32917816, 2020). "Besides, the deletion of Sphk2 was recently shown to prevent aged mice from insulin resistance, at least in part, due to elevated adipose tissue lipolysis." (PMID 32917816, 2020). "Indeed, hepatic ceramide levels were comparable in control and Sphk2-LKO mice on HFD, but Sphk2-LKO mice exhibited more severe insulin resistance." (PMID 32917816, 2020). "Nevertheless, how FTY720 improves muscle insulin resistance and whether SphK2 is involved in this regulation remain elusive." (PMID 33633691, 2020). "Sphk2-LKO mice developed pronounced insulin resistance and glucose intolerance." (PMID 32917816, 2020). "Both SphK1 and SphK2 play a fundamental role in hepatic insulin resistance." (PMID 29510489, 2018). "Moreover, the implications of SphK1 and SphK2 in insulin resistance have recently emerged." (PMID 34530846, 2021). "However, roles of SphK2 and its related sphingolipids in hepatic insulin resistance remain elusive." (PMID 32917816, 2020). "However, Sphk2-LKO mice exhibited significantly elevated plasma insulin levels and enhanced homeostasis assessment of insulin resistance (HOMA-IR) values under the HFD condition." (PMID 32917816, 2020).
Insulin resistance (continued). "There is no direct experimental evidence depicting the role of SphK2 in muscle insulin resistance." (PMID 33633691, 2020).
ovarian carcinoma (7 papers, 2017 to 2022). A malignant neoplasm originating from the surface ovarian epithelium. "In addition, whether FSH-induced activation of the Erk pathway in ovarian cancer cells causes variation in SphK1 and SphK2 expression and activity is still unclear." (PMID 32796926, 2020). "In this study, we provide the first evidence that adipocytes are capable of activating SphK2 and unravel a previously unrecognized role of SphK2 in the adipocyte-induced growth-promoting action in ovarian cancer." (PMID 35178477, 2022). "FSH induces the phosphorylation of both SPHK1 and SPHK2 enzymes to regulate the survival and growth of ovarian cancer cells via the ERK1/2 pathway." (PMID 35565311, 2022). "Both SPHK1 and SPHK2 have been shown to be equally responsible for follicle-stimulating hormone (FSH)-induced cell proliferation of epithelial ovarian cancer." (PMID 35565311, 2022). "Our earlier studies showed that SphK2 is mainly located in the nucleus of ovarian cancer cells and is potentially involved in the regulation of gene activation." (PMID 35178477, 2022). "FSH stimulated the phosphorylation of both SphK1 and SphK2 and was able to regulate the survival and growth of ovarian cancer cells by activating SphK1 and SphK2 through ERK1/2." (PMID 32796926, 2020). "Additionally, the expression levels of both phospho-SphK1 and phospho-SphK2 were closely correlated with the expression level of follicle-stimulating hormone receptor (FSHR) in ovarian cancer tissues." (PMID 32796926, 2020). "Data for the function of SPHK2 in ovarian cancer cells are limited." (PMID 31891125, 2018). "However, the function of SphK2 in ovarian cancer remains largely unknown." (PMID 29088837, 2017). "We investigated the SphK1, SphK2, MVDCD34 and MVDCD105 expression in samples from ovarian cancer patients." (PMID 29088837, 2017). "We found that knockdown of SphK1, but not SphK2, by siRNA inhibited S1P secretion in ovarian cancer cells." (PMID 29088837, 2017). "SphK1, but not SphK2, blockage significantly decreased S1P release from ovarian cancer cells." (PMID 29088837, 2017). "In vitro, the angiogenic potential and angiogenic factor secretion of ovarian cancer cells could be attenuated by SphK1, but not SphK2, blockage and were restored by the addition of S1P." (PMID 29088837, 2017). "Moreover, SphK1, but not SphK2, siRNA transfection significantly attenuated the angiogenic potential and angiogenic factor secretion of ovarian cancer cells, which suggested that SphK1, but not SphK2, was involved in ovarian cancer angiogenesis." (PMID 29088837, 2017). "Moreover, SphK1, but not SphK2 knockdown, resulted in the suppression of the angiogenic potential and the angiogenic factor secretion of ovarian cancer cells, indicating that SphK1, but not SphK2, was responsible for ovarian cancer angiogenesis." (PMID 29088837, 2017). "The expression level of SphK1, but not SphK2, was closely correlated with the microvascular density (MVD) of ovarian cancer tissue." (PMID 29088837, 2017).
renal fibrosis (7 papers, 2018 to 2023). A final common manifestation of a wide variety of chronic kidney diseases characterized by glomerulosclerosis and tubulointerstitial fibrosis. "In summary, we have identified Bst1 as a downstream target of Sphk2 that has a previously unrecognized role in kidney injury and revealed that Bst1 deficiency leads to less renal fibrosis." (PMID 36267620, 2022). "Previous studies showed that SphK2, catalyzing the conversion of sphingosine to S1P, played a critical role in renal fibrosis." (PMID 36226596, 2023). "To evaluate the role of Bst1 in the context of fibrosis, we subjected Bst1–/– mice to unilateral IRI, the same method applied to Sphk2–/– mice, and found that Bst1–/– mice developed less renal fibrosis than WT controls." (PMID 36267620, 2022). "SphK1 and SphK2 differentially regulate cell proliferation and inflammation, whereas both promote renal fibrosis." (PMID 35409370, 2022). "Bst1/CD157 was identified as a gene that is regulated by SphK2 through a change in histone acetylation level, and Bst1–/– mice were found to develop less renal fibrosis after unilateral ischemia-reperfusion injury, a mouse model of kidney fibrosis." (PMID 36267620, 2022). "Taken together, these data suggest that both SphK1 and SphK2 promote renal fibrosis through different downstream signaling pathways in oxidant-induced kidney injury." (PMID 35409370, 2022). "This phenomenon is recapitulated in wild type mice treated with a specific Sphk2 inhibitor (SK2i), SLP 120701 in agreement with recent studies showing similar reductions in renal fibrosis upon Sphk2 lack or inhibition." (PMID 29518138, 2018). "In contrast, reducing S1P by knocking down SPHK2 in renal macrophages could inhibit renal fibrosis by reducing macrophage-mediated inflammatory responses." (PMID 38041133, 2023). "Sphk2–/– mice develop less renal fibrosis than Sphk1–/– mice, and S1P and SphK2 are part of a corepressor complex that influences histone acetylation and gene expression; therefore we focused on identifying targets downstream of SphK2." (PMID 36267620, 2022). "Sphk2 has previously been attributed a role in the pathogenesis of renal fibrosis." (PMID 35682566, 2022). "In contrast to the pro-fibrotic role of Sphk1, it was found that Sphk2-deficient rather than Sphk1-deficient mice were protected from folic acid or ischemia-reperfusion injury-induced renal fibrosis." (PMID 33231567, 2020). "Taken together, these results suggest that Sphk2 expression on the kidney parenchymal as well as the hematopoietic cells both contribute to drive the pro-inflammatory phenotype in WT mice, but the lack of Sphk2 expression in either tissue is sufficient to significantly reduce renal fibrosis." (PMID 29518138, 2018). "On the other hand, SphK2-knockout ameliorated I/R- and UUO-induced renal fibrosis by inhibiting TGF-β1." (PMID 35409370, 2022). "Finally, two recent studies investigated Sphk2 in renal injury by manipulating Sphk2 levels or activity in the UUO model or chemical and ischemic renal injury models whose results strongly support our findings that Sphk2 exacerbates renal fibrosis." (PMID 29518138, 2018).
psoriasis (6 papers, 2020 to 2025). An autoimmune condition characterized by red, well-delineated plaques with silvery scales that are usually on the extensor surfaces and scalp. "While these studies indicate a beneficial effect of the topical application of S1P on psoriasis, further studies exist demonstrating that inhibition of SPHK2 leads to an improvement of psoriasis." (PMID 36674974, 2023). "Sphingosine kinase 2 inhibitors ameliorated psoriasis in mice, possibly by reducing spleen weight and cell numbers (p<0.05)." (PMID 34992595, 2021). "S1P receptor agonists and sphingosine kinase 2 inhibitors could be potential methods for treating psoriasis by decreasing immune responses and inflammatory factors." (PMID 34992595, 2021). "To investigate S1P levels in psoriasis, we analyzed the expression of key S1P regulatory genes (SPHK1, SPHK2, and SGPL1) using the psoriasis dataset GSE54456." (PMID 39833165, 2025). "Our findings indicate that psoriasis can be treated by blocking S1P activity by competitively binding to S1PR and inhibiting S1P synthase activity (SPHK2 inhibitor) using a mechanism that is related to decreased immune responses and inflammatory factor levels." (PMID 34992595, 2021).
Cerebral ischemia (5 papers, 2015 to 2021). Restriction of arterial blood supply to the brain associated with insufficient oxygenation to support the metabolic requirements of the tissue. "Gene deletion studies on SphK2 showed that SphK2 was an important protective molecule after cerebral ischemia via attenuating ischemic brain damages." (PMID 34489737, 2021). "SphK2 catalyzes the majority of S1P synthesis in the brain, and an important role for SphK2 in protection against brain atrophy following cerebral ischemia has been established." (PMID 32521763, 2020). "Mice lacking SphK2, but not SphK1, exhibit enhanced brain damage and poorer neurological outcomes after transient middle cerebral artery occlusion, indicating that SPHK2 is a cytoprotective lipid kinase during cerebral ischemia." (PMID 34055895, 2021).
Hepatic steatosis (5 papers, 2021 to 2025). Steatosis is a term used to denote lipid accumulation within hepatocytes. "Mentioned effects in S1P level and SPHK2 expression were the most severe in the third and fourth weeks of high-fat feeding, suggesting that in these weeks, there is a significant inhibition in the catabolism pathway, which predisposed to the development of simple hepatic steatosis." (PMID 34830360, 2021). "We found that both WT and Sphk2-KO mice developed a similar level of hepatic steatosis upon HFHSD feeding, as reflected in H&E staining and hepatic TG and CE determination." (PMID 36333295, 2022). "Deletion of either S1PR2 or SphK2 significantly increased hepatic steatosis and inflammation." (PMID 40057751, 2025). "The decrease of hepatic FFA might result from the reduction of circulating NEFA in Sphk2-KO mice, as the latter is the primary source of the former in human fatty liver disease." (PMID 36333295, 2022). "Notably, although Sphk2 was not involved in chronic Dex-induced hepatic steatosis and hypertriglyceridemia, we cannot exclude the involvement of ERK1/2 and HDAC1/2 in this process." (PMID 40490140, 2025). "Thus, Sphk2 does not play a role in chronic Dex-induced lipid disorders and S1PR2’s role in mediating chronic Dex-induced hypertriglyceridemia and hepatic steatosis likely does not require Sphk2." (PMID 40490140, 2025). "Downstream of S1PR2 activation is the induction of sphingosine kinase 2 (SPHK2) that can translocate to the nucleus to modulate gene synthesis, and in the same study above, the authors found that Sphk2−/− mice at 20 weeks of age spontaneously develop hepatic steatosis." (PMID 34440841, 2021).
non-small cell lung carcinoma (5 papers, 2017 to 2024). A group of at least three distinct histological types of lung cancer, including non-small cell squamous cell carcinoma, adenocarcinoma, and large cell carcinoma. "Sphingosine kinase 1 (SphK1) and sphingosine kinase (SphK2) are both important therapeutic targets of non-small cell lung cancer (NSCLC)." (PMID 35831279, 2022). "Overexpression of SphK2 has been suggested to contribute to gefitinib resistance in non-small cell lung cancer (NSCLC) and all-trans retinoic acid (ATRA) resistance in colon cancer." (PMID 32670862, 2020). "Xenograft and zebrafish model showed that RPTOR blockade suppressed BM of non-small cell lung cancer (NSCLC) and impaired the SPHK2/S1P/STAT3 pathway." (PMID 38163890, 2024). "In non-small cell lung cancer (NSCLC) including A549, sphingosine kinase 2 (SphK2) is proposed to be the key regulator of sphingolipid signaling which may contribute to the apoptosis resistance." (PMID 30089463, 2018).
osteosarcoma (5 papers, 2017 to 2026). A usually aggressive malignant bone-forming mesenchymal neoplasm, predominantly affecting adolescents and young adults. "We demonstrate that SphK2 is over-expressed in multiple human osteosarcoma tissues and established human osteosarcoma cell lines." (PMID 29285269, 2017). "Silencing of SphK2 by targeted shRNAs induces cell apoptosis and inhibits osteosarcoma cell growth." (PMID 33920887, 2021). "Remarkably, forced-expression of miR-19a-3p silenced SphK2 and inhibited osteosarcoma cell growth." (PMID 29285269, 2017). "Silence of SphK2 by targeted-shRNAs inhibited osteosarcoma cell growth, and induced cell apoptosis." (PMID 29285269, 2017). "Sphingosine kinase 2 (SphK2) expression and potential functions in osteosarcoma were studied." (PMID 29285269, 2017). "On the other hand, exogenous over-expression of SphK2 could further promote osteosarcoma cell growth." (PMID 29285269, 2017).